VWF (von Willebrand factor)
Diseases named in the same sentence as VWF in open-access papers (continued):
Sharing a sentence is not in itself a finding about the gene and the disease.
heart failure (20 papers, 2010 to 2025). Inability of the heart to pump blood at an adequate rate to meet tissue metabolic requirements. "VWF trafficking and storage are sensitive to cellular and environmental stresses that are associated with heart disease and heart failure." (PMID 36901985, 2023). "Platelet activation induced by high levels of circulating von Willebrand factor in addition to elevated inflammation and oxidative stress contribute to the hypercoagulable state in heart failure." (PMID 36187010, 2022). "Plasma VWF:Ag levels have also been found to be substantially increased in patients with acute or recent decompensated cardiac failure." (PMID 34564132, 2021). "Decreased activity of ADAMTS13 with concomitant high VWF:Ag levels has also been demonstrated as an independent predictor of clinical events in patients with cardiac failure." (PMID 34564132, 2021). "This review evaluates the relationship of VWF and ADAMTS13 with cardiac disease, including cardiac failure, and associated pathophysiology." (PMID 34564132, 2021). "The trans-pQTLs associated with VWF levels were located in the ABO gene, and previous studies suggested that ABO blood groups were associated with several health and disease outcomes, e.g., hyperlipidemia, T2D, and heart failure." (PMID 36797296, 2023). "Because oxidative stress is a key trigger for the activation of the AMPK pathway, we reasoned that VWF trafficking and storage may be perturbed in microvascular endothelial cells of hearts subject to heart failure." (PMID 36901985, 2023). "Due to a previous satisfactory response to FVIII/VWF concentrate and contraindication of desmopressin in patients with cardiac insufficiency because of fluid retention, FVIII/VWF concentrate was chosen as the treatment of choice to prevent peri- and post-operative bleeding." (PMID 20707891, 2010).
Insulin resistance (20 papers, 2009 to 2024). Increased resistance towards insulin, that is, diminished effectiveness of insulin in reducing blood glucose levels. "Studies have demonstrated elevated vWF levels in patients with DM type 2 or insulin resistance, linking these increased levels to a higher risk of cardiovascular diseases." (PMID 39061644, 2024). "Decreased insulin sensitivity, due to insulin resistance, has been associated with increases in the serum levels of platelet factors, such as fibrinogen and von Willebrand factor, and thus increased potential for hypercoagulability which is a CHD hallmark." (PMID 25774201, 2015). "Indeed, glucose control and HbA1c were linked to higher vWF, F8, and procoagulant imbalance, whereas insulin resistance was related directly to F8 levels." (PMID 36313186, 2022). "Similarly, in the Coronary Artery Risk Development in Young Adults study, VWF remained associated with insulin resistance after multivariable adjustment." (PMID 27787621, 2017). "Furthermore, vWF was reported to be associated with homeostasis model assessment—insulin resistance, which is an index of insulin resistance, and MetS." (PMID 25646961, 2015). "It was also reported that vWF was associated with insulin level and insulin resistance." (PMID 25646961, 2015). "In conclusion, our data show that BAFF is an adipokine dynamically related to OB progression, insulin resistance status, and systemic inflammatory environment, and is a predictor of soluble vWF augmentation, in young overweight and obese Mexican subjects." (PMID 35629302, 2022). "Insulin resistance and chronic inflammation can trigger the activation of the coagulation cascade and increase the production of procoagulant factors such as tissue factor and von Willebrand factor, promoting thrombus formation." (PMID 39081294, 2024). "Interestingly, the component related to insulin resistance, as detected by fasting insulin levels, was independently associated with F8, but not with vWF nor with F8/PC." (PMID 36313186, 2022). "A number of disturbances have been suggested to contribute to ED in CKD including elevated blood pressure, insulin resistance, abnormalities in the nitric oxide pathway (ADMA and L-arginine), inflammation (sVCAM-1 and sE-selectin), thrombosis (vWF), and endothelial dependent dilation (FMD)." (PMID 33562195, 2021).
lung carcinoma (19 papers, 2007 to 2025). "The first panel, consisting of FGB, FGG, and VWF proteins, exhibits promise as a diagnostic tool for the early detection of lung cancer." (PMID 37953280, 2023). "This consolidated the literature data on an association of increased VWF and/or decreased ADAMTS‐13 with worse survival probability in colorectal cancer, cancer of the head and neck, lung cancer, and in Waldenström's macroglobulinemia." (PMID 31294335, 2019). "The best three single gene discriminators are CAV1, SFTPC and VWF for lung cancer, having the same classification accuracy, 99.1% on the training set and 98.2% and 100%, 96.3% and 82.5%, and 88.9% and 100% on the two test sets, respectively." (PMID 21060876, 2010). "Immunostaining of human tissue from lung cancer brain metastases also revealed that KCa channel expression was colocalized with vWF expression in tumor capillary endothelia." (PMID 17359538, 2007). "Besides, scientists pay attention to explore the relationship between the expression level of VWF and lung cancer." (PMID 33968738, 2021). "Interestingly, a previous study of lung cancer showed that ADAM28 can downregulate vWF and cleave proapoptotic VWF in carcinoma cells, thereby increasing lung metastasis." (PMID 25886574, 2015). "Indeed, studies of tumorigenic properties in a vWF-null mouse with lung cancer revealed a potential protective role for vWF against metastasis." (PMID 25886574, 2015). "The increase of VWF and the decrease of ADAMTS-13 promote the invasion and metastasis of lung cancer." (PMID 36181128, 2022). "Conversely, seven of the downregulated hub genes (TLR4, PECAM1, SELP, CXCL12, VWF, KDR, and CD34) showed both low expression and good prognosis in lung cancer patients (p < 0.05)." (PMID 33627711, 2021). "More recently, it was found that aggressive breast and lung cancer cells with high levels of ADAM28 (a disintegrin and metalloproteinase 28) are able to avoid VWF-induced apoptosis at micrometastatic sites." (PMID 25846632, 2015). "To address this question, we examined KCa channel and endothelial cell marker von Willebrand factor (vWF) expression in CRL-5904 tumors and human lung cancer brain metastases tissue." (PMID 17359538, 2007). "Furthermore, we analyzed the correlation of the expression of hub gene in lung cancer tissues, of which PECAM1, VWF, CD34, COL1A1, MMP9 and TIMP1 are closely related." (PMID 33850663, 2021). "Indeed, raised vWF levels are not specific to ILD and are consistently observed across a range of diseases such as cholangiocarcinoma, lung cancer, and oral squamous cell carcinoma." (PMID 40750896, 2025).
microangiopathic hemolytic anemia (19 papers, 2013 to 2025). "Acquired TTP is primarily caused by autoantibodies leading to the accumulation of large von Willebrand factor (vWF) multimers causing platelet aggregation and microangiopathic hemolytic anemia (MAHA)." (PMID 34055510, 2021). "TTP is a rare microangiopathic hemolytic anemia in which mutations of vWF protease (ADAMTS13) or autoantibodies against ADAMTS13 lead to the deposition of von Willebrand factor (vWF) multimers within capillaries." (PMID 33919576, 2021). "This von Willebrand factor (vWF) cleaving protease deficiency is due either to autoantibodies directed against the protein in the acquired form of the disease, or to biallelic mutations of the encoding gene in the inherited form (also termed Upshaw-Schulman syndrome)." (PMID 26081109, 2015). "Congenital thrombotic thrombocytopenic purpura (cTTP) is an extremely rare recessively inherited disease linked to the mutation of ADAMTS-13, a gene coding for a von Willebrand factor (VWF)-cleaving protease (ADAMTS-13)." (PMID 39995752, 2025). "The ADAMTS13 deficiency leads to the accumulation of high molecular weight vWF multimers, which in turn, form platelet rich clots that cause TMA lesions and microangiopathic hemolytic anemia." (PMID 25429351, 2014). "Congenital thrombotic thrombocytopenic purpura (cTTP; Upshaw-Schulman syndrome) is an ultra-rare disorder caused by severe deficiency of ADAMTS13, the metalloprotease responsible for cleaving ultra-large von Willebrand factor (UL-VWF) multimers." (PMID 41458739, 2025). "Hereditary thrombotic thrombocytopenic purpura (hTTP), also known as Upshaw–Schulman syndrome, is a rare genetic disorder caused by mutations in the ADAMTS13 gene that leads to decreased or absent production of the plasma von Willebrand factor (VWF)-cleaving metalloprotease ADAMTS13." (PMID 37895305, 2023).
systemic lupus erythematosus (19 papers, 2009 to 2025). An autoimmune multi-organ disease typically associated with vasculopathy and autoantibody production. "Some studies provided evidence of the relationship between higher levels of VWF or Lupus Anticoagulant and a higher risk of fatal events in these patients." (PMID 41585277, 2025). "A potential stimulatory effect of aPL on VWF secretion has been described, resulting in higher VWF levels in patients with systemic lupus erythematosus and APS." (PMID 39726607, 2024). "The VWF:Ag level and VWF:RCo values were higher in patients with systemic lupus erythematosus (primarily in those with serositis) than those in healthy controls." (PMID 36531725, 2022). "In this regard, autoantibodies to von Willebrand factor (VWF) have been described in patients with systemic lupus erythematosus (SLE) or monoclonal gammopathy." (PMID 25170428, 2014). "First-line laboratory tests were performed and then were followed by further tests included mixing study, lupus anticoagulant testing, clotting factor activity assay, von Willebrand Antigen (VW: Ag), Ristocetin co factor vWF: RiCoF activity and platelet function test." (PMID 30774827, 2018). "The high activity of vWf in lupus may thus be attributable to both pro-inflammatory cytokines and to autoantibodies, and could directly contribute to the high incidence of CVE in SLE." (PMID 20003285, 2009). "The activities of factors II (FII), V (FV), VII (FVII), VIII (FVIII), IX (FIX), X (FX), XI (FXI), and von Willebrand factor (VWF, both antigen and activity) were all within normal ranges, while the lupus anticoagulant standardized ratio was 1.3." (PMID 41574369, 2025). "In addition, several autoimmunity-related proteins are linked to coagulation (e.g., AGT, F2) and to specific ADs, such as systemic lupus erythematosus (e.g., AGT, C1S, C7, MMP2, VWF) or autoimmune rheumatic diseases (e.g., ADIPOQ, AGT, MASP1, MMP2)." (PMID 40546301, 2025). "Remarkably, FVIII:C was lower than the VWF:Ag level, and the FVIII increase was lower than expected after administering FVIII/VWF concentrate, which appeared to be due to a lupus-like anticoagulant activity, with a prolonged APTT lupus and increasing levels of FVIII in serial dilution studies." (PMID 34095769, 2021).
liver cirrhosis (18 papers, 2011 to 2025). "The imbalance in the ADAMTS13 enzyme–VWF substrate (i.e., the decrease in ADAMTS13 activity (ADAMTS13:AC) and increase in VWF antigen (VWF:Ag)) was associated with the severity of liver cirrhosis (LC), acute liver failure (ALF), and severe alcoholic hepatitis." (PMID 36829443, 2023). "It was long believed that the role of platelets in patients with liver cirrhosis was solely to promote aggregation and form the primary haemostatic plug after adhering to the damaged vessel walls through an interaction with von Willebrand factor." (PMID 38279183, 2024). "ADAMTS13 specifically cleaves the multimeric von Willebrand factor (VWF), and an imbalance between ADAMTS13 activity (ADAMTS13:AC) and VWF antigen (VWF:Ag) levels is associated with the severity of liver cirrhosis (LC)." (PMID 35407443, 2022). "As a biomarker of endothelial function, several studies have reported that the vWF level is related to the progression of liver cirrhosis." (PMID 35360443, 2022). "The proteolytic mechanism that reduces VWF multimers also occurs in those with aortic valve stenosis, pancreatitis, liver cirrhosis, and leukemia." (PMID 30068378, 2018). "Ongoing investigations in our laboratory have indicated that patients with liver cirrhosis show even higher levels of elevated vWF:Ag and vWF activity than the patients with GC reported herein (data not shown)." (PMID 25886574, 2015). "We aimed to investigate the influence of vWF on primary hemostasis in patients with liver cirrhosis." (PMID 25397410, 2014). "In patients with fulminant hepatic failure and liver cirrhosis, circulating plasma VWF antigen levels are extremely high." (PMID 21526182, 2011). "Cases with liver cirrhosis have been observed to have elevated VWF titers." (PMID 40764410, 2025). "Similarly, few studies have shown that patients with liver cirrhosis have lower levels of high molecular weight VWF multimers." (PMID 37143635, 2023). "Based on the Cox regression model, a newly developed MELD-vWF-Ag model was obtained, and ROC curve analysis showed that the incorporation of vWF-Ag into the MELD scoring system can increase the possibility of clinically relevant predictions of mortality in patients with liver cirrhosis." (PMID 35360443, 2022). "Indeed, elevated plasma vWF:Ag levels have been reported in cases of acute liver injury/failure, alcoholic hepatitis, liver cirrhosis, and sickle cell disease." (PMID 25886574, 2015). "Endotoxemia in patients with liver cirrhosis has shown to increase vWF-levels." (PMID 25397410, 2014). "We propose that increased cardiac output associated with ESRD, due to dialysis arteriovenous fistula, and liver cirrhosis, due to peripheral vasodilation, may result in increased shear stress across dysfunctional PV, leading to an abnormality in VWF multimers and GI bleeding." (PMID 37143635, 2023). "To determine prognostic factors for patients with liver cirrhosis in the post-ACLF group, we performed multivariate analysis using VWF:Ag/ADAMTS13:AC, CLIF-C ACLF score, Cre, and MELD score, which had p-values <0.1 in the univariate analysis." (PMID 36829443, 2023).
migraine (18 papers, 2010 to 2026). "Furthermore, in a mendelian randomization study, genetically determined increased levels of hemostatic factors FVIII, von Willebrand factor (vWF), phosphorylated fibrinopeptide A, and a decrease of fibrinogen seemed causally related to susceptibility for migraine, especially migraine with aura." (PMID 34858141, 2021). "Some of these (e.g., nitric oxide, ET-1, vWF, platelet-activating factor, and homocysteine) have been consistently implied in migraine pathogenesis, especially in MA." (PMID 36923493, 2023). "A number of studies have demonstrated increased VWF antigen levels and activity in patients with migraine compared with healthy controls, prompting the idea that migraine may be less frequent in patients with VWD." (PMID 41536292, 2026). "While women with migraine often show higher platelet activity and elevated fibrinogen and VWF levels compared with those without migraine, this association is inconsistent." (PMID 40022462, 2025). "In the present study, the differences between hsCRP, CIMT, vWF antigen, vWF activity, nitrite, nitrate and isoprostants levels had a positive correlation with migraine frequency (although it only reached statistical significance in the case of CIMT, vWF antigen, vWF activity)." (PMID 37940678, 2023). "Moreover, biomarker levels improved in treatment-responsive patients with migraine; hsCRP levels decreased from 2.54 to 1.69 mg/dL (p < 0.05), vWF activity levels decreased from 124 to 103 IU/dL (p = 0.003) and prothrombin activity decreased from 1.01 to 0.93 (p = 0.01)." (PMID 37940678, 2023). "Several observations suggest that endothelial function is abnormal in migraine patients, including an increased prevalence of anti-endothelial cell antibodies that may induce endothelial damage and raised plasma levels of ET-1 and von Willebrand factor." (PMID 23566281, 2013). "Studies have shown increased levels of Von Willebrand factor (VWF), platelet-activating factor and platelet aggregation during migraine episodes." (PMID 33083518, 2020). "The other two participants, who had elevated factor VIII levels and increased von Willebrand factor activity, did not experience any migraine‐related benefits from anticoagulation." (PMID 39989443, 2025).
vasculitis (18 papers, 2009 to 2025). "Reports of increased serum levels of von Willebrand factor (vWF) in active vasculitis also strengthen this notion." (PMID 41441888, 2025). "Primarily secreted by endothelial cells, the vWF can serve as a biomarker for endothelial injury and dysfunction in pathological states such as vasculitis." (PMID 39061644, 2024). "In this study, JDM patients with eyelid marginal blood vessel dilation were 32% more likely to have elevated vWF:Ag, supporting the use of vWF:Ag as a biomarker for vasculitis in JDM." (PMID 36831088, 2023). "Also, the low NK cell group displayed a significantly higher von Willebrand factor antigen level, which is a biomarker of vasculitis in a subset of JDM patients, compared with JDM patients whose NK levels were normal." (PMID 39000234, 2024). "A murine model of immune complex-mediated vasculitis and irritant contact dermatitis showed that the interference with vWF activity with vWF-blocking antibody led to a substantial decrease in vWF-mediated leukocyte recruitment and reduction of cutaneous inflammatory response." (PMID 33096906, 2020). "Von Willebrand factor antigen levels increase in serum in response to endothelial injury or activation; therefore, monitoring of VWF levels may reflect disease activity in many vasculitis." (PMID 32719754, 2020). "More recently, a study of VWF in adult patients with AAV and renal involvement observed high levels of VWF in patients with active vasculitis that persisted even when they were considered in clinical remission." (PMID 28785984, 2018). "Neither complement levels (C3, C4), serum vasculitis markers (von Willebrand factor and D-dimer), nor autoantibodies differed significantly between males and females." (PMID 35998241, 2022). "Importantly, these patients have significantly higher plasma levels of vWF than patients without vasculitis and the normal subjects." (PMID 26247590, 2015). "In addition, two of the three patients who underwent genetic sequencing were found to have abnormal genetic deoxyribonucleic acid (DNA) sequences, including VWF mutation in patient 3 and CLCN5 mutation in patient 10, which could not explain the occurrence of vasculitis." (PMID 38357518, 2024).